EGFR (epidermal growth factor receptor)
Diseases named in the same sentence as EGFR in open-access papers (continued):
Sharing a sentence is not in itself a finding about the gene and the disease.
tumor (continued). "Preclinical studies have shown that IORT influences wound response by downregulating miR-223, which in turn reduces the activation of the epidermal growth factor receptor and disrupts the tumor growth-stimulating loop." (PMID 39439951, 2024). "While YTHDF2 knockdown has been shown to inhibit HCC cell proliferation, other studies have highlighted its tumor-suppressive role by targeting genes such as EGFR, IL11, and SRPINE2." (PMID 38395751, 2024). "IHC staining with anti-EGFR mAb revealed a low to very high expression of EGFR within the tumor areas." (PMID 39406917, 2024). "Amivantamab is a bispecific monoclonal antibody that prevents tumor growth and progression by blocking EGFR and c-MET pathways and stimulates immune-mediated destruction of EGFR and cMET-expressing cells." (PMID 38605928, 2024). "Injection of the anti-EGFR-MPB solution illuminated a distinct region within the tumor and blood vessels." (PMID 39525484, 2024). "Based on 2022 guidelines from the American Society of Clinical Oncology, the decision to initiate anti-EGFR treatment should be guided by the primary tumor location and testing for BRAF and RAS (KRAS and NRAS) mutations and deficient mismatch repair or MSI2." (PMID 38347302, 2024). "Abnormal activation of receptor proteins in the RTKs family (such as EGFR and PDGFR) is associated with various tumors and is also an important target for tumor drug research." (PMID 38495504, 2024). "Key biomarkers such as MGMT promoter methylation, IDH1/2 mutations, EGFR amplification, and TERT promoter mutations, etc., are examined for their roles in prognosis, therapeutic response, and tumor classification." (PMID 39767571, 2024). "CBL proteins exert anti-tumor effects by facilitating the degradation of several well-known tyrosine kinases with tumor-promoting roles, such as EGFR and HER2." (PMID 39342146, 2024). "The ADC inhibited cell cycle progression, induced cytotoxicity against high EGFR-expressing tumor cells, and bystander killing of neighboring EGFR-low tumor cells, but minimal effects on immune cells." (PMID 38772416, 2024). "Recent studies have proposed that driver mutations, such as EGFR mutations or RHOA mutations, are associated with the immunosuppressive tumor microenvironment." (PMID 38455493, 2024). "MET amplification is a common root of tumor escape from inhibition of other tyrosine kinases, which is particularly well exemplified for EGFR TKIs." (PMID 38966170, 2024). "The genetic alterations in oncogenic pathways, such as mutations in genes like EGFR, KRAS, and BRAF, can impact the immune response in the tumor microenvironment." (PMID 39045411, 2024). "The median time from advanced diagnosis to first-line treatment initiation for patients with cEGFRm, ex20ins, and EGFR wild type tumours was 0.8 months, 2.5 months, and 1.5 months, respectively." (PMID 38668049, 2024). "Genome-wide scans of tumor lesions identified 161 and 53 genes and miRNAs, which code for EGFR/MAPK signaling, cell proliferation, oncomirs and oncogenes, and 50% of DEGs code for immune response and tumor evasion." (PMID 38245882, 2024). "Because combination of Bevacizumab with EGFR TK inhibitors showed improved tumor response, we assessed the combined effect of osimertinib plus bevacizumab in these three tumor models of NSCLC." (PMID 38935790, 2024). "As discussed, the effect of GHRH-R antagonists and EGFR inhibitors has been shown to reduce cell viability and tumour growth of xenografts of different tumour types, including prostatic." (PMID 39456984, 2024). "Our results showed that Z239-1907 inhibited tumor cell growth, which blocked the activation of the Axl–EGFR signaling pathway in NPC cells." (PMID 39594573, 2024).
tumor (continued). "Apart from the immune microenvironment, we also explore the hallmarks of residual EGFR-mutant tumor cells and interaction with immune cells after neoadjuvant immunochemotherapy." (PMID 38897205, 2024). "For their epidermal growth factor receptor (EGFR) tyrosine kinase activity, triazole-substituted quinazoline derivatives have been produced and have shown modest activity in tumor cell lines (HCT116, MCF-7, and PC-3)." (PMID 38671909, 2024). "This is per other studies that show that EGFR expression was downregulated with increasing grade of tumor in OSCC." (PMID 39050298, 2024). "In tumor ECs, increased EGFR and reduced ErbB3 expression result in greater cellular proliferation and vascular growth." (PMID 38892305, 2024). "This can occur due to factors such as the effects of anti-tumor therapies or the use of tyrosine kinase inhibitors that inhibit the activity of epidermal growth factor receptor (EGFR) or anaplastic lymphoma kinase (ALK)." (PMID 38462628, 2024). "For instance, fetal tumor organoids were selectively targeted by EGFR inhibitors, whereas embryonal organoids were targeted by FGFR inhibitors." (PMID 39567475, 2024). "JNJ-61186372 exhibited anti-tumor effects in wild-type and mutant EGFR and c-MET pathway activation scenarios." (PMID 39664377, 2024). "Overall, our findings indicate that BCL2L1/BCL-XL expression is important for tumor cell survival as EGFR-TKI resistance emerges." (PMID 39122703, 2024). "Across the range of markers studied, one of the most promising is EGFR, with its overexpression or aberrant activation potentially leading to uncontrolled cell growth and tumor development." (PMID 39459468, 2024). "In relation to tumor stages, EGFR showed overexpression in stages 3 and 4 compared to normal samples, with statistically significant differences noted between stage 1 and stages 3–4, as well as between stage 2 and stage 4." (PMID 39594688, 2024). "The pharmacological or genetic inhibition of EGFR in different models of hepatic injury ending in HCC prevents tumor development." (PMID 38473265, 2024). "Studies have shown that anti-EGFR therapy can induce tumor-specific adaptive immune responses and immunogenic cell death." (PMID 39050571, 2024). "There was also a reduction in tumor regrowth after drug withdrawal in the EGFR-mutant PDX model TH021, LU-01-1291, and LU1868, with no indication of substantial overall toxicity in preliminary studies." (PMID 38702301, 2024). "In cancer cells, GOLM1 has the ability to be released into the cytoplasm and acts as a molecular chaperone to interact with various tumour‐related molecules such as EGFR, RTK, MMP2, MMP7 and B3‐H7, exerting a pro cancer effect." (PMID 39470578, 2024). "Among them, 11C-erlotinib and 18F-afatinib showcased the most promising tumor-to-background contrast in EGFR-positive lesions, while 11C-osimertinib exhibited the highest SUV and tumor-to-background ratio AUC values across various tissues." (PMID 38892979, 2024). "The patients with EGFR mutations reported a high Treg infiltration, reduced CD8 + T-cell number and decreased tumor mutation burden (TMB), which induced a poor clinical efficacy of ICI." (PMID 38402169, 2024). "Preclinical pharmacodynamic studies have demonstrated the effective inhibition of EGFR signaling by erlotinib, resulting in reduced tumor growth in animal models." (PMID 38611728, 2024). "Preclinical findings suggested that this molecule obtained high‐affinity binding to CD16a and showed therapeutic effectiveness in various EGFR‐expressing tumour cells." (PMID 39472273, 2024). "Tumours that have epidermal growth factor receptor (EGFR) amplification, telomerase reverse transcriptase (TERT) promoter mutation, or concurrent chromosome 7 gain/chromosome 10 loss exhibit a clinical course similar to that of GBM." (PMID 39099691, 2024).
tumor (continued). "Our comprehensive proteogenomic analyses revealed a nuanced understanding of the tumor microenvironment in NSLA patients devoid of oncogenic EGFR and ALK alterations." (PMID 39300154, 2024). "HA and CD44’s connection encourages epidermal growth factor receptor-mediated pathways, which therefore results in the growth of tumor cells, tumor cell migration, and chemotherapy resistance." (PMID 39026213, 2024). "Mutations in EGFR, human epidermal growth factor receptor-2 (HER-2), or Kirsten rat sarcoma virus oncogene homolog (KRAS) result in increased tumor cell proliferation and diminished apoptosis." (PMID 39872524, 2024). "The interaction of HA and CD44 promotes EGFR-mediated pathways, consequently leading to tumor cell growth, tumor cell migration, and chemotherapy resistance in breast, prostate, and gastrointestinal cancers." (PMID 39840036, 2024). "Tumor-derived EVs interact with endothelial cells to exhibit proangiogenic activities by delivering activated EGFR." (PMID 39403600, 2024). "Simultaneous magnetic resonance imaging (MRI) analysis demonstrated decreased tumor growth, setting the stage for future investigations into the potential of novel therapeutic strategies for EGFR-mutant ADCs." (PMID 38546390, 2024). "The detected EGFR mutations included three Ex19del and three L858R mutations in 12 CTC samples and five Ex19del and three L858R mutations in 12 tumor tissue samples, respectively." (PMID 39335743, 2024). "The results demonstrated that NKCEs that bivalently target both EGFR and NKp30 were superior to monovalent NKCEs in promoting NK cell-mediated tumor cell lysis." (PMID 39911822, 2024). "The antibodies retain their affinity for EGFR and their anticancer properties in tumor cell lines, thus addressing this challenge." (PMID 38248333, 2024). "In an in vivo study, vandetanib was reported to induce tumor regression in patient-derived xenograft ER-negative BC models, expressing high levels of EGFR or RET (rearranged during transfection) through the inhibition of EGFR phosphorylation." (PMID 38892472, 2024). "The results demonstrate that the anti-tumor activity of Tandyukisin is largely achieved by targeting EGFR." (PMID 38751788, 2024). "We notice that either EGFR TKI or RAPGEF3 inhibitor alone has marginal inhibitory effect on tumor growth, whereas the antitumor effect is dramatically enhanced upon combinational therapy in RAPGEF3high tumors." (PMID 39687207, 2024). "Intriguingly, APT-β1 significantly enhanced the anti-tumor effect of Gefitinib (100 mg/kg/day, p.o.), a tyrosine kinase inhibitor targeting mutant EGFR, suggesting potential synergy in combination therapies to combat lung cancer." (PMID 38675493, 2024). "Experimental models using animal models with tumour cell xenografts have shown that blocking EGFR increases tumour cell mortality, reduces angiogenic factor production, and prolongs survival." (PMID 38773634, 2024). "EGFR antibody to generate ADCs, which showed potent antitumor efficacy in a synthetic mouse tumor model and exhibited good tolerability." (PMID 38817608, 2024). "While treatment with the MEK inhibitor pimasertib only slightly reduced tumor growth, treatment with the EGFR inhibitor cetuximab effectively reduced cancer proliferation by more than 70%." (PMID 38966179, 2024). "Glycosylphosphatidylinositol (GPI) anchor proteins, commonly occurring on cell membranes and expressed on EV membranes, can bind to anti- EGFR nanobodies, enabling the targeting of tumor cells overexpressing EGFR." (PMID 39802949, 2024). "In that time, it is possible that the tumor developed a detectable population with amplification of EGFR." (PMID 38605523, 2024).
tumor (continued). "It has also been reported that in GBM, the overall prevalence of EGFRvIII in patients with EGFR gene amplification ranges from 50% to 60% and contributes to tumor stem cell maintenance." (PMID 39195222, 2024). "In the research articles examined, apoptosis is primarily induced through the regulation of the expression of microRNAs, tumor suppressors, EGFR, cell cycle proteins, and anti-apoptotic proteins, among others." (PMID 39872524, 2024). "The proliferative ability and function of CD8+ T cells were attenuated when co-cultured with EGFR mutant tumor cells compared with wild-type tumor cells." (PMID 39004699, 2024). "The results of this retrospective analysis indicate that tumor location has an impact on the potential treatment of CRC with anti-EGFR therapy." (PMID 38409377, 2024). "Another study described the use of the C225 antibody to target the epidermal growth factor receptor (EGFR) in a mouse tumor model overexpressing this receptor (A549)." (PMID 38791253, 2024). "We find that BCL2L1, which encodes the anti-apoptotic protein BCL-XL, is highly expressed predominantly in tumor cells, where it likely plays a crucial role in tumor cell survival as drug tolerance and acquired resistance to EGFR-TKIs emerge." (PMID 39122703, 2024). "EGFR is a cell surface receptor that plays a vital role in regulating tumor metastasis by activating downstream signaling pathways, including the MAPK pathway and the PI3K/Akt pathway." (PMID 38762741, 2024). "Mel 767 VR tumors retained an up-regulated EGFR phenotype with a mean tumor H‐score of 189.9/300 respect to Mel 767 P tumors with a mean tumor H‐score of 75.8/300." (PMID 38510242, 2024). "Further, combination therapy with Bcl-2 and PKC-I siRNA loaded into the anti-EGFR QLs significantly hindered tumor growth and metastatic spread." (PMID 39199788, 2024). "Degalactotigonin inhibits the EGFR signaling pathway to induce apoptosis and cell cycle arrest, and the Hedgehog/Gli1 Pathway to inhibit tumor cell migration and invasion." (PMID 39155844, 2024). "Under EGFR mutation conditions and prolonged exposure to EGFR‐TKIs, phosphorylated ERRFI1 ceases to operate as a tumor suppressor; instead, it actively promotes the survival of cancer cells." (PMID 39096122, 2024). "A larger collection of normal samples and tumor samples with paired tumor-adjacent tissues need to be examined to better elucidate the potential toxicity of targeting EGFR and MUC1." (PMID 39664199, 2024). "For example, the EGFR-mediated signaling pathway plays a crucial role in tumor cell proliferation, that influences cellular activities, such as nuclear transcription and mitochondrial metabolism." (PMID 38844562, 2024). "WGS of the posttreatment tissue revealed that the ecDNA-driven hyperamplification of EGFR reached more than 80 copies, which likely amplified the wild-type EGFR allele, suggesting dual independent activating mechanisms of the MAPK pathway in this tumor." (PMID 39138315, 2024). "EGFR-Vδ2 bsTCEs have displayed compelling activation of Vγ9Vδ2 T cells which induce cytotoxicity against EGFR+ tumor cells." (PMID 38576617, 2024). "Among the listed key targets, EGFR has excellent binding activity, which can be the focus of subsequent research on the anti-tumor and anti-inflammatory activities of SR." (PMID 39022612, 2024). "Its antibody shows promise as a therapeutic target by inhibiting both EGFR-mediated and non-EGFR-mediated pathways to suppress tumor growth." (PMID 39399490, 2024). "Both types of EGFR-targeted QLs increased delivery to target tumor cells with more efficient gene silencing and tumor imaging than non-targeted control QLs." (PMID 39199788, 2024). "Binding kinetics were measured using two different EGFR and PD-L1 double-positive tumor cell lines, A431 and A549." (PMID 38804304, 2024).
tumor (continued). "For cancer angiogenesis, EVs secrete vascular endothelial growth factor (VEGF) and disseminate epidermal growth factor receptor (EGFR) molecules for activation within the tumor microenvironment." (PMID 39639879, 2024). "EGFR labeling was primarily observed in the cytoplasms and cell membranes of both tumor and normal cells, with the labeling being homogeneous along the cell periphery." (PMID 38785565, 2024). "Cetuximab blocks the binding of epidermal growth factor to its receptor, inhibiting the EGFR signaling pathway critical for tumor growth and survival." (PMID 39123466, 2024). "miRNA-1 is a tumor suppressor that is highly conserved and targets multiple pathways, including members of the tyrosine kinase receptor family such as c-met and EGFR." (PMID 38200584, 2024). "The EGFR signaling pathway is often aberrantly activated in cancer cells and contributes to unregulated cancer cell proliferation and tumor growth." (PMID 38673992, 2024). "Targeting the EGFR pathway in anti-tumor therapies has demonstrated significant improvements in the survival rates of NSCLC patients." (PMID 39375945, 2024). "DEA results further supported our categorization of the left area as a tumor region, evident from the presence of marker genes such as EGFR, and the right area as cortex, characterized by neural marker genes like SNAP25." (PMID 39179527, 2024). "Some studies directly link the reduction or loss of ANXA1 in HSCC to tumor development and other HNSCC-related oncogenes such as EGFR and miR-196a/b." (PMID 38893148, 2024). "GHRH receptors (GHRH-R), which are coupled to G-proteins (GPCRs), can mediate EGFR transactivation, offering an alternative pathway for tumour survival." (PMID 39456984, 2024). "NuF is confirmed to be able to inhibit tumor EGFR activation and the expression of HIF-2α and PTHrP." (PMID 39273055, 2024). "We examined 34 tumor sections from various dog breeds to assess the immunoexpression of Cox-2 and EGFR." (PMID 38248333, 2024). "A novel nanoparticle‐based tri‐specific NKCE (nano‐TriNKCE) targeting EGFR‐overexpressing tumours has been developed using a PEG–PLGA matrix, modified with cetuximab and co‐functionalised with anti‐CD16 and anti‐4‐1BB antibodies." (PMID 39472273, 2024). "Monalizumab is administered either as a monotherapy or in combination with other therapeutic antibodies, such as durvalumab, which targets PD-L1, or cetuximab, which targets the epidermal growth factor receptor (EGFR) expressed by tumor cells." (PMID 39584993, 2024). "Here, in order to mimic tumor initiation, clonal expression of constitutively active version of EGFR (EGFRλ condition) coupled to GFP was realized in approximatively 1% of the accessory gland cells." (PMID 38893271, 2024). "Here TSO500 detected a ROS1 fusion and EGFR: p.Leu861Gln in two cases, with 12% and 29% tumor content, respectively." (PMID 38398180, 2024). "Because of its relevance in a large variety of neoplastic diseases, EGFR has long been considered as an attractive therapeutic target." (PMID 39329717, 2024). "Chromogenic and fluorescent IHC (GFAP, CD45 and EGFR).Further characterisation of CTC and associated tumour: comparative genomic hybridization, sequence analysis and FISH." (PMID 38481938, 2024). "Our analysis supports this clinical practice, as we observed differences in EGFR mAb efficacy based on tumour sidedness." (PMID 38402342, 2024). "C0epi contains CSCs with sustained EGFR signaling activity, thus representing a tumor-initiating cluster, that we named START (Stem Tumor initiAtor egfR clusTer)." (PMID 38546390, 2024). "Due to ethical issues, expression of EGFR was analyzed in the tumor samples from the patients taken at first surgery or puncture after diagnosis." (PMID 39653700, 2024). "Both PD-L1 and EGFR can be upregulated on the surface of HCC tumour cells and antibodies targeting the PD-1: PD-L1 axis are approved in HCC." (PMID 39286025, 2024).